ZC3HC1 (zinc finger C3HC-type containing 1)
Description:
Required for proper positioning of a substantial amount of TPR at the nuclear basket (NB) through interaction with TPR.
Synonyms: NIPA; HSPC216
Tractability: PROTAC: ubiquitination databases record sites on it; its protein half-life has been measured.
Gene: Protein-coding gene on chromosome 7 (130,018,286 to 130,051,401, reverse strand). Ensembl gene ENSG00000091732.
Subcellular location: Nucleus; Nucleus envelope
Subcellular location (Human Protein Atlas): Nuclear membrane; Nucleoplasm
Pathways (Reactome):
Disease: Nuclear events stimulated by ALK signaling in cancer
Gene Ontology:
Molecular function: protein binding; protein kinase binding; zinc ion binding
Cellular component: nuclear envelope; nuclear membrane; nuclear pore nuclear basket; nucleoplasm; nucleus
Genetic constraint (gnomAD): Loss-of-function variants: 36 observed, 58.69 expected, observed/expected ratio (o/e) 0.61, 90% interval 0.47 to 0.81. The upper end of that interval is the gene's LOEUF score, 0.81, which puts it in group 3 of 6, group 1 being the genes least tolerant of losing a copy. Missense variants: 551 observed, 651.83 expected, observed/expected ratio (o/e) 0.85, 90% interval 0.79 to 0.91. Synonymous variants: 212 observed, 241.86 expected, observed/expected ratio (o/e) 0.88, 90% interval 0.78 to 0.98.
Homologues: Orthologues: chimpanzee ZC3HC1 (99% identical), macaque ZC3HC1 (99% identical), pig ZC3HC1 (90% identical), rabbit ZC3HC1 (86% identical), dog ZC3HC1 (86% identical), rat Zc3hc1 (86% identical), guinea pig ZC3HC1 (85% identical), mouse Zc3hc1 (85% identical), tropical clawed frog zc3hc1 (51% identical), zebrafish zc3hc1 (45% identical), Caenorhabditis elegans npp-27 (14% identical).
Diseases named in the same sentence as ZC3HC1 in open-access papers:
ZC3HC1 is named in the same sentence as 27 diseases in open-access papers, as found by Europe PMC text mining. Sharing a sentence is not in itself a finding about the gene and the disease. The quoted sentences say what the papers report.
coronary artery disease (5 papers, 2016 to 2024). "At present, there are many researches about the association between SMARCA4 and ZC3HC1 and coronary heart disease." (PMID 31507094, 2019). "SMARCA4 (OMIM: 603254) and ZC3HC1 (OMIM: 603254) are high‐risk genes for coronary heart disease." (PMID 31507094, 2019). "We identified colocalizing signals for increased coronary artery disease risk and increased MPV in a missense coding mutation for ZC3HC1/NIPA." (PMID 32600345, 2020).
essential hypertension (2 papers, 2019 to 2025). Hypertension that presents without an identifiable cause. "ZC3HC1 is closely related to the risk of developing essential hypertension through endothelial dysfunction." (PMID 39824883, 2025). "For the current study, we evaluated the association between eight SNPs in SMARCA4 and ZC3HC1 and hypertension risk, and aimed to find the relations of these SNPs and hypertension risk in Han Chinese population." (PMID 31507094, 2019). "Kunnas and Nikkari (2015) reported the association of ZC3HC1 rs11556924 genetic variant with hypertension in a Finnish population." (PMID 31507094, 2019). "However, few studies have examined the association between SMARCA4 and ZC3HC1 and hypertension risk." (PMID 31507094, 2019). "Therefore, in our research, we studied the relationship between ZC3HC1 SNPs (rs2242487, rs1464890, and rs4507892) and hypertension in Chinese Han population, and we found that the polymorphism of ZC3HC1 (rs1464890) has a strong protective effects on the hypertension." (PMID 31507094, 2019). "In this study, we aimed to evaluate the association between genetic variants of ZC3HC1 and SMARCA4 and hypertension risk in the Chinese Han population." (PMID 31507094, 2019). "Our results suggest that rs1464890 and rs4507692 (ZC3HC1), rs11879293 (SMARCA4) and rs1122608 (SMARCA4) were conducive to play a protective role to against the risk of hypertension." (PMID 31507094, 2019). "The present study suggested that ZC3HC1 and SMARCA4 polymorphism may conducive to play a protective role against the hypertension risk." (PMID 31507094, 2019).
rheumatoid arthritis (2 papers, 2016 to 2024). A chronic, systemic autoimmune disorder characterized by inflammation in the synovial membranes and articular surfaces. "Another missense variant, rs11556924 (His363Arg), in ZC3HC1 may alter cell cycle entry and was associated with carotid intima-media thickness in rheumatoid arthritis (RA) patients." (PMID 27386823, 2016).
colon carcinoma (1 paper, 2021). "Furthermore, we disrupted the ZC3HC1 alleles in HCT116 cells, a near-diploid male cell line derived from a primary colon carcinoma, as a representative of the endodermal lineage." (PMID 34440706, 2021).
osteosarcoma (1 paper, 2021). A usually aggressive malignant bone-forming mesenchymal neoplasm, predominantly affecting adolescents and young adults. "Therefore, we knocked out all ZC3HC1 alleles in U-2 OS cells too, which represent a hyper-triploid, chromosomally highly altered female cell line that stems from an osteosarcoma (; see also characteristics for the U-2 OS [ATCC HTB-96] cell line at) and is therefore of mesodermal origin as well." (PMID 34440706, 2021).
Stroke (1 paper, 2021). Sudden impairment of blood flow to a part of the brain due to occlusion or rupture of an artery to the brain. "This list includes the DNA damage and apoptosis factor ZC3HC1, which is implicated in MI and stroke." (PMID 33554857, 2021).
cancer (3 papers, 2022 to 2025). A tumor composed of atypical neoplastic, often pleomorphic cells that invade other tissues. "This suggests that, at least in human fibroblasts, ZC3HC1 may not play the structural role in establishing interconnections between TPR polypeptides at the nuclear basket which has been reported in cancer cells." (PMID 40443800, 2025).
tumor (3 papers, 2015 to 2024). "In addition, such a knockdown of ZC3HC1 had been also described as accounting for cell cycle arrest in prometaphase, and as triggering apoptosis, especially in tumour cells like HeLa." (PMID 34440706, 2021). "Furthermore, also upon shutdown of gene transcription in tumour cells, ZC3HC1 remained located at the NE, together with TPR." (PMID 34440706, 2021). "Similarly, after having destructed the ZC3HC1 gene in several human cell lines by CRISPR/Cas9n technology, we did not note any generally obvious growth phenotype, in line with genome-scale CRISPR KO screens in human tumour cell lines." (PMID 34440706, 2021).
ZC3HC1 also shares sentences with these, for which no sentence is quoted: endothelial dysfunction (2 papers); infection (2); lymphoma (2); alcohol dependence (1); atherosclerosis (1); bone marrow failure (1); breast carcinoma (1); Fanconi anemia (1); heart failure (1); Hypertension (1); ischemic stroke (1); lung carcinoma (1); lymphatic disease (1); multiple myeloma (1); myocardial infarction (1); Obesity (1); oesophageal cancer (1); Prader-Willi syndrome (1); type 2 diabetes (1).